LIN37 (lin-37 DREAM MuvB core complex component)
Synonyms: ZK418.4; F25965; lin-37
Tractability: PROTAC: UniProt records ubiquitination sites on it; ubiquitination databases record sites on it.
Gene: Protein-coding gene on chromosome 19 (35,748,361 to 35,754,519, forward strand). Ensembl gene ENSG00000267796.
Subcellular location (Human Protein Atlas): Nucleoplasm
Pathways (Reactome):
Cell Cycle: Cyclin A:Cdk2-associated events at S phase entry; Cyclin E associated events during G1/S transition; G0 and Early G1; G1/S-Specific Transcription; Polo-like kinase mediated events; Transcription of E2F targets under negative control by DREAM complex; Transcription of E2F targets under negative control by p107 (RBL1) and p130 (RBL2) in complex with HDAC1
Gene Ontology:
Molecular function: protein binding; protein-containing complex binding
Biological process: negative regulation of DNA-templated transcription; negative regulation of transcription by RNA polymerase II; positive regulation of transcription by RNA polymerase II; regulation of DNA-templated transcription
Cellular component: nucleoplasm; DRM complex; Myb complex; nucleus; RNA polymerase II transcription regulator complex; transcription repressor complex
Genetic constraint (gnomAD): Loss-of-function variants: 21 observed, 34.28 expected, observed/expected ratio (o/e) 0.61, 90% interval 0.43 to 0.88. The upper end of that interval is the gene's LOEUF score, 0.88, which puts it in group 3 of 6, group 1 being the genes least tolerant of losing a copy. Missense variants: 273 observed, 321.94 expected, observed/expected ratio (o/e) 0.85, 90% interval 0.77 to 0.94. Synonymous variants: 126 observed, 120.29 expected, observed/expected ratio (o/e) 1.05, 90% interval 0.91 to 1.21.
Homologues: Orthologues: chimpanzee LIN37 (99% identical), macaque LIN37 (99% identical), dog LIN37 (98% identical), guinea pig LIN37 (97% identical), pig LIN37 (97% identical), mouse Lin37 (95% identical), rat Lin37 (94% identical), rabbit LIN37 (79% identical), tropical clawed frog lin37 (55% identical), zebrafish lin37 (43% identical), Drosophila melanogaster mip40 (18% identical).
Diseases named in the same sentence as LIN37 in open-access papers:
LIN37 is named in the same sentence as 6 diseases in open-access papers, as found by Europe PMC text mining. Sharing a sentence is not in itself a finding about the gene and the disease. The quoted sentences say what the papers report.
diabetes (1 paper, 2024). "Although Wnt10 and Lin37 are not directly related to the occurrence of diabetes and morbid obesity, the results of the PPI network analysis showed that these genes directly interact with genes associated with the development of T2DM, such as Mybl1." (PMID 38396669, 2024).
embryonal carcinoma (1 paper, 2011). A non-seminomatous malignant germ cell tumor characterized by the presence of large germ cells with abundant cytoplasm resembling epithelial cells, geographic necrosis, high mitotic activity, and pseudoglandular and pseudopapillary structures formation. "In mouse embryonal carcinoma cells knock-down of lin-9 or lin-54 resulted in significant cell cycle defects, while knock down of lin-37 or lin-52 had no such effects." (PMID 21570388, 2011).
Parkinson disease (1 paper, 2024). A progressive degenerative disorder of the central nervous system characterized by loss of dopamine producing neurons in the substantia nigra and the presence of Lewy bodies in the substantia nigra and locus coeruleus. "Wnt10a, which is associated with both Parkinson’s disease and fat accumulation, exhibits a direct correlation with the inflammatory cytokine gene Lin37." (PMID 38396669, 2024).
cancer (3 papers, 2017 to 2022). A tumor composed of atypical neoplastic, often pleomorphic cells that invade other tissues. "Considering that p130/p107 and Lin37 are connected through their function in transcriptional repression, Lin37 may be inactivated only in specific types of cancer or be alternatively mutated to p130 or p107." (PMID 28920576, 2017). "While some cancer tissues show reduced Lin37 levels compared to normal tissue (e.g. testis, ovary), others show no significant alteration (e.g. skin, lung) or even an upregulated Lin37 expression (e.g. breast, pancreas)." (PMID 28920576, 2017). "This indicates a role of Lin37 in cell transformation and cancer development." (PMID 28920576, 2017). "In order to investigate whether a reduced Lin37 expression contributes to cancer formation in specific tissues, additional studies such as experiments in a Lin37 knockout mouse model have to be conducted." (PMID 28920576, 2017). "Similarly, we revealed that TERC promotes cellular inflammatory response by upregulating the expression of immune-related genes such as LIN37, TPRG1L, TYROBP and USP16 in human normal and cancer cells." (PMID 31294790, 2019).
tumor (3 papers, 2017 to 2025). "The synMuv B genes encode homologues of the dREAM complex, which are conserved across animals and plants, including the LIN-35/retinoblastoma (Rb) tumor suppressor, and the Rb complex components LIN-53 /RbAp48, LIN-37/MIP40, LIN-54/MIP120, DPL-1 /DP, LIN-9/MIP130." (PMID 39879188, 2025).
LIN37 also shares sentences with these, for which no sentence is quoted: morbid obesity (1 paper).